KPNB1 (karyopherin subunit beta 1)
Description:
Functions in nuclear protein import, either in association with an adapter protein, like an importin-alpha subunit, which binds to nuclear localization signals (NLS) in cargo substrates, or by acting as autonomous nuclear transport receptor. Acting autonomously, serves itself as NLS receptor. Docking of the importin/substrate complex to the nuclear pore complex (NPC) is mediated by KPNB1 through binding to nucleoporin FxFG repeats and the complex is subsequently translocated through the pore by an energy requiring, Ran-dependent mechanism. At the nucleoplasmic side of the NPC, Ran binds to importin-beta and the three components separate and importin-alpha and -beta are re-exported from the nucleus to the cytoplasm where GTP hydrolysis releases Ran from importin. The directionality of nuclear import is thought to be conferred by an asymmetric distribution of the GTP- and GDP-bound forms of Ran between the cytoplasm and nucleus. Mediates autonomously the nuclear import of ribosomal proteins RPL23A, RPS7 and RPL5. In association with IPO7, mediates the nuclear import of H1 histone. In vitro, mediates nuclear import of H2A, H2B, H3 and H4 histones (By similarity). Imports MRTFA, SNAI1 and PRKCI into the nucleus. (Microbial infection) In case of HIV-1 infection, binds and mediates the nuclear import of HIV-1 Rev.
Synonyms: NTF97; IPOB; MGC2155; MGC2156; MGC2157; IMB1; Impnb; IPO1
Tractability: Small molecule: a structure with a bound ligand is known; it has a binding pocket of medium quality. Antibody: its Gene Ontology location is reachable by antibodies, with high confidence. PROTAC: ubiquitination databases record sites on it; its protein half-life has been measured.
Gene: Protein-coding gene on chromosome 17 (47,649,476 to 47,685,505, forward strand). Ensembl gene ENSG00000108424.
Subcellular location: Cytoplasm; Nucleus envelope
Subcellular location (Human Protein Atlas): Nuclear membrane; Cytosol; Nucleoplasm
Pathways (Reactome):
Disease: Inhibition of nitric oxide production; Maturation of DENV proteins; Maturation of hRSV A proteins; NS1 Mediated Effects on Host Pathways; Nuclear import of Rev protein; SARS-CoV-1 activates/modulates innate immune responses; Transport of Ribonucleoproteins into the Host Nucleus
Immune System: ISG15 antiviral mechanism; Interferon alpha/beta signaling; Neutrophil degranulation
Cell Cycle: Initiation of Nuclear Envelope (NE) Reformation; Postmitotic nuclear pore complex (NPC) reformation
DNA Replication: Assembly of the ORC complex at the origin of replication
Metabolism: Regulation of cholesterol biosynthesis by SREBP (SREBF)
Programmed Cell Death: Apoptosis induced DNA fragmentation
Gene Ontology:
Molecular function: enzyme binding; nuclear import signal receptor activity; protein binding; protein domain specific binding; RNA binding; nucleocytoplasmic carrier activity; zinc ion binding; Hsp90 protein binding; importin-alpha family protein binding; small GTPase binding
Biological process: astral microtubule organization; establishment of mitotic spindle localization; mitotic chromosome movement towards spindle pole; mitotic metaphase chromosome alignment; mitotic spindle assembly; NLS-bearing protein import into nucleus; protein import into nucleus; ribosomal protein import into nucleus; RNA import into nucleus; positive regulation of cholesterol biosynthetic process; regulation of cholesterol biosynthetic process; intracellular protein transport
Cellular component: cytoplasm; cytosol; endoplasmic reticulum tubular network; extracellular exosome; membrane; NLS-dependent protein nuclear import complex; nuclear envelope; nuclear membrane; nucleoplasm; cytoplasmic stress granule; extracellular region; ficolin-1-rich granule lumen; nuclear pore; specific granule lumen; protein-containing complex
Genetic constraint (gnomAD): Loss-of-function variants: 4 observed, 76.9 expected, observed/expected ratio (o/e) 0.052, 90% interval 0.025 to 0.12. The upper end of that interval is the gene's LOEUF score, 0.12, which puts it in group 1 of 6, group 1 being the genes least tolerant of losing a copy. Missense variants: 317 observed, 853.32 expected, observed/expected ratio (o/e) 0.37, 90% interval 0.34 to 0.41. Synonymous variants: 299 observed, 320.92 expected, observed/expected ratio (o/e) 0.93, 90% interval 0.85 to 1.02.
Homologues: Orthologues: chimpanzee KPNB1 (100% identical), rabbit KPNB1 (99% identical), mouse Kpnb1 (99% identical), pig KPNB1 (99% identical), rat Kpnb1 (99% identical), guinea pig KPNB1 (99% identical), macaque KPNB1 (98% identical), tropical clawed frog kpnb1 (95% identical), zebrafish kpnb1 (92% identical), Drosophila melanogaster Fs(2)Ket (62% identical), Caenorhabditis elegans imb-1 (49% identical). Paralogues in human: IPO4 (19% identical), IPO5 (17% identical), RANBP6 (16% identical), TNPO1 (15% identical), TNPO2 (14% identical).
Diseases named in the same sentence as KPNB1 in open-access papers:
KPNB1 is named in the same sentence as 51 diseases in open-access papers, as found by Europe PMC text mining. Sharing a sentence is not in itself a finding about the gene and the disease. The quoted sentences say what the papers report.
glioblastoma (11 papers, 2018 to 2024). The most malignant astrocytic tumor (WHO grade IV). "Several reports revealed that KPNB1 was associated with the progression of various tumors, including glioblastoma, breast cancer, CRC, and non-small cell lung cancer." (PMID 39148981, 2024). "The nuclear import receptor karyopherin β1 (encoded by KPNB1) is involved in drug resistance in various cancer cells, including B-cell lymphoma, glioblastoma, ovarian, and esophageal carcinoma cells." (PMID 33801927, 2021). "UPR-induced upregulation of Puma, Noxa, and Bak results in the remodeling of mitochondrial network in KPNB1-deficient glioblastoma cells." (PMID 29520102, 2018). "This postulation is supported by the upregulated polyubiquitination of both p65 and total proteins, ALIS formation, and upregulated p65/chaperones interactions in KPNB1-deficient glioblastoma cells." (PMID 29520102, 2018). "These suggest that reducing total protein amount in KPNB1-deficient glioblastoma cells by translation inhibition via mechanisms like ER stress aims at restoring proteostasis, whereas chronic ER stress upregulates pro-apoptotic Bcl-2 proteins and induces apoptosis." (PMID 29520102, 2018). "It is noteworthy that circPITX1’s role as a miR-584-5p sponge substantiates its involvement in regulating KPNB1 expression in glioblastoma (GBM) cells." (PMID 37841446, 2023). "Previous studies showed that heat shock protein 70, an important regulator of protein degradation, accumulated in the cytoplasm in KPNB1-silenced glioblastoma cells." (PMID 35902727, 2022). "KPNB1 transported DR5 into the nucleus, while inhibition of KPNB1 restored DR5 levels on the cell surface of glioblastoma cells." (PMID 31022877, 2019). "In the present study, we delineate the molecular basis of KPNB1 inhibition in modulating TRAIL vulnerability of glioblastoma cells." (PMID 30742128, 2019). "Genetic or pharmacological inhibition of KPNB1 potentiated TRAIL-induced apoptosis selectively in glioblastoma cells mainly by unfolded protein response (UPR)." (PMID 30742128, 2019). "Taken together, our findings demonstrate that KPNB1 is required for proteostasis maintenance and its inhibition induces apoptosis in glioblastoma cells through UPR-mediated deregulation of Bcl-2 family members." (PMID 29520102, 2018). "We further investigated the effect of importazole (IPZ), a small molecule that inhibits KPNB1-mediated protein nuclear import, in four glioblastoma cell lines (U87, U251, A172, and SHG-44) and human fetal astrocytes (HA)." (PMID 29520102, 2018). "To investigate this point, we depleted KPNB1 using three short hairpin RNA (shRNA) constructs (shKPNB1-1, 2, and 3) targeting human KPNB1 in U87 and U251 glioblastoma cells." (PMID 29520102, 2018). "Together, these findings suggest that knockdown or pharmacological inhibition of KPNB1 suppresses glioblastoma cell viability." (PMID 29520102, 2018). "In glioblastoma cells, KPNB1 depletion inactivates Mcl-1 by downregulating Mcl-1 expression and inducing expression of Mcl-1-bound BH3-only proteins, leading to the activation of Bax and Bak." (PMID 29520102, 2018). "Our results in glioblastoma cells demonstrate that KPNB1 inhibition perturbs proteostasis, triggers the autophagy-lysosomal and ubiquitin-proteasomal-mediated protein degradation, and probably chaperone-mediated protein folding for adaption to stress." (PMID 29520102, 2018). "Together, these results suggest that KPNB1 deprivation in glioblastoma cells impairs protein nuclear import and perturbs proteostasis, which govern the intensity of UPR and apoptosis." (PMID 29520102, 2018). "RAN and its partner KPNB1 regulate nuclear import of their cargos to promote glioblastoma cell survival and to induce drug resistance in patients." (PMID 30671385, 2018).
glioblastoma (continued). "In glioblastoma research, KPNB1 knockdown inhibited β-catenin nuclear import, resulting in the inactivation of the Wnt/β-catenin signaling pathway and the arrest of proliferation, and targeting KPNB1 alleviated TRAIL resistance." (PMID 39414762, 2024). "Another study illustrated that cicPITX1/miR-584-5p/KPNB1 axis could regulate glioblastoma progression through mediating the proliferation, migration, invasion, angiogenesis, and cell cycle." (PMID 36455873, 2022). "It has been previously reported that KPNB1 inhibition caused impaired cellular proteostasis and increased ubiquitination of both p65 and total proteins in glioblastoma cells, which suggested that KPNB1 probably had functions similar to the deubiquitination enzyme." (PMID 35902727, 2022). "Thus, blocking autophagy-lysosomal degradation prevents cleaved caspase-8 from clearance and markedly augmented the synergism of KPNB1 inhibitor/TRAIL combination in glioblastoma cells." (PMID 30742128, 2019). "KPNB1 inhibition-induced autophagy protects glioblastoma cells from proteotoxicity." (PMID 30742128, 2019). "Moreover, combination of Bcl-xL inhibitors and KPNB1 inhibition enhanced apoptosis in glioblastoma cells." (PMID 29520102, 2018). "Upregulation of KPNB1 has been observed in cancers including glioblastoma." (PMID 29520102, 2018). "In this study, we show that KPNB1 is required for glioblastoma survival." (PMID 29520102, 2018). "Inhibitors of Bcl-xL rather than Bcl-2 enhances KPNB1 inhibitor-induced apoptosis in glioblastoma cells, suggesting that combination of Bcl-xL inhibitors and KPNB1 inhibitors, such as IPZ and INI-43, may be efficacious and safe for solid tumors therapy." (PMID 29520102, 2018). "KPNB1 inhibition abrogates ABT-263 resistance in glioblastoma cells." (PMID 29520102, 2018). "In summary, our studies identify KPNB1 as a target for apoptosis induction in glioblastoma cells and suggest that KPNB1 inhibition, alone or in combination with inhibitors of Bcl-xL, lysosome, or proteasome, may serve as promising therapeutic strategies for glioblastoma treatment." (PMID 29520102, 2018). "We demonstrated previously that KPNB1 inhibition perturbed proteostasis and activated PERK signaling branch of unfolded protein response (UPR) in glioblastoma cells." (PMID 30742128, 2019). "DR4 is lowly expressed in glioblastoma cells and less important for apoptosis by TRAIL and KPNB1 inhibition." (PMID 30742128, 2019). "We found that KPNB1 inhibition activated PERK/eIF2α/ATF4 signaling in both human and rat glioblastoma cells." (PMID 29520102, 2018). "Therefore, KPNB1 may play a role in the progression of glioblastomas." (PMID 29520102, 2018). "Furthermore, KPNB1 knockdown did not change the mitotic exit of cells released from mitotic block, suggesting that KPNB1 knockdown did not cause mitotic arrest in glioblastoma cells." (PMID 29520102, 2018). "KPNB1 knockdown upregulated total DR4 and DR5 in all tested glioblastoma cell lines." (PMID 30742128, 2019). "Here, we found that downregulation and functional inhibition of KPNB1 in glioblastoma cells induced growth arrest and apoptosis without apparent mitotic arrest." (PMID 29520102, 2018). "Taken together, our results suggest that inhibition of KPNB1 in glioblastoma cells induced apoptosis and abnormal mitosis, but not the mitotic arrest due to weak SAC activity." (PMID 29520102, 2018). "In consistent with the previous study, KPNB1 inhibition-induced upregulation of Noxa and Puma and apoptosis in glioblastoma cells depends on ATF4 but not CHOP." (PMID 29520102, 2018). "Moreover, bioinformatics analysis indicated that KPNB1 mRNA expression had moderate negative correlation with that of ATF4 in glioblastoma multiforme but not low grade glioma." (PMID 30742128, 2019).
glioblastoma (continued). "Importantly, inhibition of KPNB1 promotes glioblastoma cell apoptosis without evident prior mitotic arrest, which resembles observations in breast cancer cells but not in cervical cancer cells, suggesting a cell-type-specific manner." (PMID 29520102, 2018). "However, HA here could not represent mature astrocytes because levels of KPNB1 and glioblastoma stem cell markers Oct4 and CD133 in HA was similar to those in U87 and U251." (PMID 29520102, 2018). "Bioinformatics analysis supported a negative correlation between mRNA expression of KPNB1 and LC3B in glioblastoma multiforme." (PMID 30742128, 2019). "Consistently, in our study, KPNB1 shRNAs (shKPNB1–1, 2) or specific inhibitor importazole (IPZ) potentiated TRAIL cytotoxicity in A172, U87, U118, U251 human glioblastoma cells but not in human fetal astrocytes (HA)." (PMID 30742128, 2019).
breast carcinoma (9 papers, 2018 to 2025). "GO analysis of these genes showed strong enrichment in similar signaling pathways and biological processes to those of KPNB1 inhibition in breast cancer." (PMID 40671262, 2025). "KPNB1 has been shown to stimulate proliferation of cancer cells in various cancers, including breast cancer, prostate cancer, gastric cancer, colon cancer, and ovarian cancer." (PMID 39062749, 2024). "Previous studies have shown that KPNB1 expression is elevated in transformed ovarian cells, cervical cancer, ovarian cancer and breast cancer." (PMID 37186134, 2023). "KPNB1 overexpression has been reported in several cancers including comorbidities we identified with significant genes and pathways (breast cancer, colorectal cancer, lung cancer, ovarian cancer, and prostate cancer)." (PMID 33924631, 2021). "Among several cancers (lung cancer, prostate cancer, and breast cancer) applied for radiation therapy, a poor prognosis in lung adenocarcinoma was observed in patients with high levels of KPNB1." (PMID 32276424, 2020). "We identified components of a cytonuclear transport system, including importins KPNA2 and KPNB1, as well as a subunit of the NPC RANBP2, as binding partners of ARID1B in breast cancer cells." (PMID 40671262, 2025). "Consequently, we identified five putative breast cancer RNA-binding proteins (PUF60, TFRC, KPNB1, NSF, and SF3A3) showing strong tumorigenic characteristics." (PMID 35453681, 2022). "Thus, based on their tumorigenic characteristics presented in this study and their roles in other cancer types, we identified five new putative breast cancer RBPs: PUF60, TFRC, KPNB1, NSF, and SF3A3." (PMID 35453681, 2022).
glioma (9 papers, 2018 to 2025). A benign or malignant brain and spinal cord tumor that arises from glial cells (astrocytes, oligodendrocytes, ependymal cells). "Since KPNB1 is highly expressed in gliomas and associated with poor prognosis, we hypothesized that it may have a tumorigenic role in gliomas." (PMID 38254206, 2024). "Similar to the study on glioma, the role of KPNB1 in HCC was found to be dependent on the activation of Wnt/β-catenin signaling." (PMID 39414762, 2024). "Further analysis using the CGGA database found that KPNB1 levels were positively associated with the WHO grade of the glioma, with higher KPNB1 expression in WHO IV gliomas than those graded as WHO II or WHO III." (PMID 38254206, 2024). "The effects of KPNB1 knockdown on the tumorigenic properties of glioma cells were characterized by colony formation assays, Transwell migration assay, EdU proliferation assays, CCK-8 viability assays, and apoptosis analysis using flow cytometry." (PMID 38254206, 2024). "Of particular interest is miR-584-5p’s capacity to suppress KPNB1, consequently affecting the modulation exerted by KPNB1 on glioma proliferation and cell cycle progression." (PMID 37841446, 2023). "KPNB1 is a nuclear transport receptor, which regulates glioma proliferation via the Wnt/β-Catenin pathway." (PMID 29880060, 2018). "Additionally, we used a GBM tissue microarray to verify the positive correlation between USP7 and KPNB1 expression in gliomas." (PMID 38254206, 2024). "Analyzing the clinical characteristics of glioma patients in the TCGA database showed that KPNB1 expression was not related to age and gender but associated with the initial glioma treatment efficacy." (PMID 38254206, 2024). "Therefore, our data demonstrated that KPNB1 was upregulated in glioma tissues compared to healthy tissues, with high KPNB1 expression levels associated with poor prognosis among glioma patients." (PMID 38254206, 2024). "KPNB1 has also been previously studied in glioma; KPNB1 could regulate the proliferation of GBM cells through the Wnt/β-catenin pathway." (PMID 38254206, 2024). "Besides, KPNB1 could also directly interact with β-catenin to promote cell proliferation in human glioma cells." (PMID 35902727, 2022). "A tissue microarray was used to measure the expression of KPNB1 and USP7 in glioma tissues." (PMID 38254206, 2024). "The findings demonstrated that KPNB1 was upregulated in glioma tissues compared to non-tumor brain tissues." (PMID 38254206, 2024). "The results showed that KPNB1 expression was increased in glioma tissues compared with normal brain tissues." (PMID 38254206, 2024). "The high expression of KPNB1 in GBM could promote the growth, proliferation, and migration of glioma cells and enhance tumor growth in vivo." (PMID 38254206, 2024). "Moreover, additional analysis of the TCGA database showed that KPNB1 expression was negatively correlated with the overall survival rate of patients, a relationship that became more statistically significant with increasing WHO glioma grade." (PMID 38254206, 2024). "Transcriptome sequencing demonstrated that KPNB1 could regulate the expression of NLGN3, which has been previously reported as a postsynaptic membrane protein that is highly expressed in the central nervous system and key to glioma progression." (PMID 38254206, 2024). "Furthermore, the Kaplan–Meier curves revealed significant differences in survival for KPNB1, with the higher expression having the poorer survival, not only in all glioma samples, but also the GBM sample subset." (PMID 29520102, 2018).